TNF (tumor necrosis factor)
Diseases named in the same sentence as TNF in open-access papers (continued):
Sharing a sentence is not in itself a finding about the gene and the disease.
psoriasis (continued). "This dietary pattern effectively modulates key cytokines involved in psoriasis pathogenesis, including IL-17, IL-23, and TNF-α." (PMID 40243475, 2025). "Adalimumab (ADM) is a fully human monoclonal antibody against TNF‐α, used in the treatment of moderate to severe psoriasis." (PMID 40478194, 2025). "Results showed that IFN-γ, TNF-α, IL-1β, IL-6, IL-17A, IL-18, and IL-23 in psoriasis patients had significantly higher levels compared to controls and a strong correlation between PASI scores and these cytokines." (PMID 40699767, 2025). "Hidradenitis suppurativa and psoriasis share common inflammatory pathways, including the TNF-alpha and IL-23/IL-17 axis." (PMID 40546629, 2025). "In contrast, “psoriasis-like” lesions emerge during treatment with anti-TNF antibodies, which is the standard therapy for rheumatoid arthritis, Crohn’s disease, and psoriasis." (PMID 41153754, 2025). "Recent studies emphasize the pivotal role of T helper Th-17 and Th-1 cells in the pathogenesis of psoriasis, with interleukin IL-17A, IL-23, and tumor necrosis factor-alpha (TNF-α) serving as central mediators of skin inflammation." (PMID 40748586, 2025). "Psoriasis is predominantly mediated by pro-inflammatory cytokines, including TNF-α, IL-17, IL-22, and IFN-γ, secreted by activated T cells." (PMID 40922376, 2025). "Due to proinflammatory cytokines, such as IL-17, IL-23 and TNF-a existent in patients with psoriasis and MS, endothelial cell function is destroyed." (PMID 40003621, 2025). "In the study, genistein suppressed the expression of inflammatory factors via the downregulation of STAT3 phosphorylation in imiquimod-induced psoriasis skin lesions in mice as well as in TNF-α-stimulated HaCaT cells." (PMID 40429704, 2025). "A previous report showed that TNF-α and IL-6 levels are higher in psoriasis patients compared to healthy individuals." (PMID 40733073, 2025). "Evidence has been provided in multiple investigations for the involvement of the WNT/β-catenin pathway and TNF-α in the pathophysiology of psoriasis." (PMID 39910492, 2025). "TNF targeting therapy has been beneficialin avoiding atherosclerosis in RA, and it is possible that this is also the casein psoriasis." (PMID 40160593, 2025). "Although psoriasis and polymyositis are different diseases, they share similar pathologies, involving abnormal T cell function and the production of TNF-α and IL-17." (PMID 40441209, 2025). "Together with IL-17A, TNF-α plays a central role in regulating the expression of cytokines and keratinocyte genes, thereby modulating keratinocyte function in psoriasis." (PMID 40343299, 2025). "While mimicking the complex pathological features of psoriasis is challenging, and several models have been developed to study psoriasis in vitro, TNF-α alone was used in our study to induce pathological mechanisms in an in vitro environment." (PMID 40507893, 2025). "TNF-α plays a crucial role in many inflammatory diseases (asthma, atopic dermatitis, psoriasis, many forms of arthritis, and other autoimmune/inflammatory conditions)." (PMID 40869088, 2025). "Materials and Methods: This review synthesizes the current evidence on key salivary cytokines—IL-1β, IL-6, TNF-α, and IL-17—in relation to psoriasis pathogenesis, diagnosis, and treatment monitoring." (PMID 40731810, 2025). "For instance, in psoriasis, Th1 cells can secrete tumor necrosis factor (TNF)-α, while Th22 cells secrete interleukin (IL)-22, and Th17 cells secrete IL-17, IL-22, and TNF-α." (PMID 40862458, 2025). "For example, sustained GOS intake for 10 weeks significantly reduced pro-inflammatory cytokines IL-1, IL-6, and TNF-α while increasing anti-inflammatory IL-10, leading to improved inflammatory symptoms of psoriasis." (PMID 41425939, 2025). "The main types of biologics available for psoriasis treatment include tumor necrosis factor (TNF) inhibitors, interleukin-17A inhibitors, and interleukin-23 inhibitors." (PMID 41179072, 2025).
psoriasis (continued). "Two patients (out of the eighteen with documented outcomes) experienced serious adverse events upon restarting anti-TNF therapy: one had an anaphylactic infusion reaction and another developed severe psoriasis, necessitating discontinuation of the anti-TNF." (PMID 40868182, 2025). "In RA, anti-TNF agents such as infliximab and adalimumab effectively suppress synovial inflammation and prevent joint destruction, while in PsA and psoriasis they also reduce cutaneous lesions and halt structural progression." (PMID 40649852, 2025). "A network meta-analysis has demonstrated that the efficacy of deucravacitinib in treating psoriasis is comparable to TNF-α inhibitors and IL-12/23 inhibitors, but lower than the more recent biologics of IL-17 inhibitors and IL-23 inhibitors." (PMID 40095888, 2025). "The inhibition of TNF-α has been proven to have a significant effect on relieving psoriasis symptoms." (PMID 40430037, 2025). "Shared inflammatory mechanisms, particularly elevations in pro-inflammatory cytokines such as IL-6, TNF-α, and IL-17, underpin the connection between psoriasis and psychiatric disorders." (PMID 40428224, 2025). "Adalimumab, a monoclonal antibody against TNF-α, is highly effective in moderate-to-severe plaque psoriasis and psoriatic arthritis, improving Psoriasis Area and Severity Index (PASI) scores and patient quality of life." (PMID 41155329, 2025). "Emerging evidence indicates a bidirectional link between psoriasis and chronic periodontitis, both driven by dysregulated immune responses and elevated proinflammatory cytokines such as TNF-α and IL-17." (PMID 41155812, 2025). "Several parameters pivotal inflammatory factors in psoriasis have been observed in this study, including IL-6, IL-17, TNF-α, and VEGF." (PMID 38712377, 2025). "Some studies investigated the presence of several disease-specific inflammatory cytokines such as TNF, IL-1β, IL-17A, IL-23, and other cytokines in patients with psoriasis, which were elevated compared to controls." (PMID 39775226, 2025). "The Inhibition of IL-17A and TNF-α was observed to improve the condition of psoriasis and enhance quality of life." (PMID 40892753, 2025). "Tumor necrosis factor-α: TNF-α is a proinflammatory cytokine central to psoriasis/PsA and also found in inflamed muscle tissue." (PMID 40861474, 2025). "In vitro experiments confirmed that MDMs derived from psoriasis patients overexpressed pyroptosis-related molecules (Caspase 1 and Caspase 4) as well as pro-inflammatory cytokines (TNFα, IL6, IL1β) when compared to healthy controls." (PMID 40722833, 2025). "Psoriasis is characterized by an exaggerated immune response, with proinflammatory cytokines such as TNF-α, IL-1, and IL-6 contributing to disease pathogenesis through sustained inflammation." (PMID 40678620, 2025). "In psoriasis, resistin is involved in the disease’s progression and development via the release of pro-inflammatory cytokines including IL-6, IL-2, and TNF-α." (PMID 40724556, 2025). "Due to increased TST reactivity, IGRA is preferred in psoriasis patients who are candidates for anti-TNF therapy." (PMID 40711067, 2025). "The specific distribution of the rash, particularly on the palms and soles, is characteristic of pustular psoriasis, leading to a suspicion of TNF inhibitor-induced psoriasis." (PMID 40678000, 2025). "TNF-α plays a central role not only in RA but also in related immune-mediated disorders, including psoriasis and psoriatic arthritis (PsA), where shared inflammatory pathways drive both skin and joint pathology." (PMID 40649852, 2025). "It binds to and inhibits tumor necrosis factor alpha (TNF-α) to prevent an inflammatory reaction and is used to treat conditions such as RA, psoriasis, and Crohn’s disease." (PMID 40143035, 2025).
psoriasis (continued). "This hormone further regulates immune cells and cutaneous cells, promoting the release of core pro-inflammatory cytokines such as IL-6, IL-17, and TNF-α, ultimately exacerbating the severity of psoriatic lesions and prolonging the chronicity of psoriasis." (PMID 41357183, 2025). "Psoriasis and inflammatory myopathies share immunopathogenic pathways, including the IL-17/IL-23 axis, type I interferons, and TNF-α." (PMID 40861474, 2025). "Several key cytokines, including TNF-α, IL-12/IL-23, and IL-17A, play a crucial role in the pathogenesis and development of psoriasis." (PMID 40520230, 2025). "In psoriasis, the IL-17/IL-23 axis, TNF-α, and interleukin-6 (IL-6) are known to contribute to the development of MetS." (PMID 40870891, 2025). "Psoriasis is a chronic, immune-mediated, inflammatory disease characterized by dysregulation of the tumor necrosis factor (TNF)-α/interleukin (IL)-23/IL-17 axis, affecting approximately 2–4% of the global population." (PMID 40333159, 2025). "In psoriasis, biological therapies approved for treatment include anti-TNF-alpha, and anti-IL-12,- IL-23, and -IL-17 agents." (PMID 40422272, 2025). "Among the future therapeutic directions are biologic therapies, including TNF-α inhibitors, as well as anti-IL-17 and anti-IL-12/23 agents, which show promising results in psoriasis and overlapping conditions." (PMID 39859462, 2025). "The introduction of biologics, such as monoclonal antibodies targeting TNF-α, IL-17, and IL-23, has markedly improved psoriasis treatment by providing highly specific and effective treatment options." (PMID 40303401, 2025). "HCV induces the production of inflammatory cytokines such as cathelicidin, TLR9, IFNγ, TNF-α, and IL-6, all of which are key contributors to psoriasis pathogenesis." (PMID 40724556, 2025). "Among numerous cytokines involved in the pathogenesis of psoriasis, TNF-α and IL-17A are particularly significant due to their synergistic effects in amplifying chronic inflammation." (PMID 40892753, 2025). "In psoriasis, dendritic cells secrete interleukin-12 (IL-12) and IL-23, while Th1 cells secrete tumor necrosis factor-alpha (TNF-α) and interferon-gamma (IFN-γ), and Th17 cells secrete interleukin-17 (IL-17) and interleukin-22 (IL-22)." (PMID 40585669, 2025). "The pathophysiology of psoriasis is complicated, involving an abnormal immune response with elevated cytokine levels like tumor necrosis factor alpha (TNF-alpha) and interleukin-6." (PMID 40370872, 2025). "In psoriasis, cytokines including tumor necrosis factor-alpha (TNF-α), interleukin-17 (IL-17), and IL-23, along with the chemokine CCL20, significantly contribute to disease initiation and progression." (PMID 40303401, 2025). "The IMQ treatment reportedly induces IL-17 A and TNFα expressions in the skin; these cytokines are essential for the development of psoriasis." (PMID 40481552, 2025). "According to previous clinical data analysis, macrophage markers and inflammatory cytokines such as TNF-α, IL-1β, IL-17A, and IL-23A are highly expressed in skin samples from psoriasis patients." (PMID 40362523, 2025). "Biologics approved by the United States Food and Drug Administration (FDA) for the treatment of psoriasis include inhibitors of tumor necrosis factor (TNF)-α." (PMID 40109802, 2025). "This activation initiate differentiation of Th22 and Th17 cell subsets, result in generation of a cascade of psoriasis-associated cytokines including interferon-gamma (IFN-γ), TNF-α, IL-22, and IL-17." (PMID 40818978, 2025). "Central cytokines driving the chronic inflammation characteristic of psoriasis include IL-17, IL-22, TNF-α, and IL-6." (PMID 40428224, 2025). "Both strategies have been shown to modulate key cytokines involved in psoriasis, such as TNF-α and IL-1β, which are central to the inflammatory processes driving the disease." (PMID 40243475, 2025).
psoriasis (continued). "These manifestations include the frequent anti-TNF-induced psoriasis and the less common anti-TNF-induced leukocytoclastic vasculitis, drug-induced lupus erythematosus, reactive arthritis/arthralgias, and drug-induced autoimmune hepatitis." (PMID 39860594, 2025). "Plaque-type psoriasis is characterized by an inflammatory pathway involving TNF-α, IL-23, and Th17 cells." (PMID 39859462, 2025). "A meta-analysis has accordingly found a higher prevalence of psoriasis in IBD patients on anti-TNF therapy." (PMID 40981083, 2025). "A significant correlation between elevated serum levels of TNF-α, IL-6 and IL-17 with psoriasis severity." (PMID 41393395, 2025). "Biologic therapies targeting TNF-α, IL-17, and IL-23 effectively control psoriasis by reducing chronic inflammation and improving skin clearance." (PMID 40282856, 2025). "Most barrier-focused studies in psoriasis have either concentrated on IL-23 pathway inhibition or a combination of different TNF-α antagonists, and detailed site-specific TEWL and pH dynamics during adalimumab monotherapy remain insufficiently characterized." (PMID 41303905, 2025). "Moderate-to-severe psoriasis patients are treated in Baltic countries predominantly with TNF inhibitors after failure of systemic conventional therapy." (PMID 40142208, 2025). "In psoriasis, their role in maintaining immune tolerance is dysregulated, as cDCs are activated under the stimulation of TNF-α, IFN-α, and the LL37 RNA complex, producing a large number of inflammatory cytokines, such as IL-12 and IL-23." (PMID 40427630, 2025). "A five-year single-center retrospective analysis conducted a single-center retrospective analysis over five years involving 200 psoriasis patients treated with either phototherapy or anti-TNFα therapy." (PMID 40692864, 2025). "The first class of biologics introduced for psoriasis treatment was TNF-α inhibitors, including adalimumab, etanercept, infliximab, and certolizumab." (PMID 41012123, 2025). "The pathophysiology of psoriasis involves the excessive release of pro-inflammatory mediators, including tumor necrosis factor-alpha (TNF-α) as well as interleukin (IL)-23 and -17 as a central mechanism." (PMID 41012123, 2025). "Its immunosuppressive mechanism specifically targets rapidly proliferating keratinocytes and attenuates the inflammatory cascade by diminishing pro-inflammatory cytokines, including TNF-α and IL-17, which are pivotal to the pathogenesis of psoriasis." (PMID 40560394, 2025). "This heightened immune response is often accompanied by elevated levels of pro-inflammatory cytokines, such as IL-6, TNF-α, and IL-17, which are also key players in psoriasis pathogenesis." (PMID 40243475, 2025). "In the case of psoriasis, for instance, related inflammatory cytokines (e.g., TNF-α and IL-6) can reach the skin and trigger an inflammatory response." (PMID 39967732, 2025). "Several autoimmune diseases have been associated with TNF inhibitor exposure, including vasculitis, SLE, and psoriasis." (PMID 40725812, 2025). "These biological agents are usually used to modulate TNF-related signaling pathways and cellular responses so that psoriasis can be alleviated." (PMID 40299379, 2025). "Biologic therapies for psoriasis, including TNF-α inhibitors, IL-17 inhibitors, and IL-23 inhibitors, are antibody-based treatments that have demonstrated substantial therapeutic efficacy." (PMID 41226338, 2025). "One such case involved a patient treated with anti-TNF drugs for psoriasis for approximately three years." (PMID 40149358, 2025). "Branisteanu and colleagues reported that in psoriasis, there is excessive production of important inflammatory mediators such as TNFα in the skin, leading to rapid cell growth and skin damage." (PMID 40343294, 2025). "Neutrophils contribute to disease progression by releasing pro-inflammatory cytokines, including TNF-α, IL-17, and IL-23—key mediators in psoriasis." (PMID 40356914, 2025).
psoriasis (continued). "The pro-inflammatory cytokines TNF-α, IL-17, and IL-6 play a crucial role in both psoriasis and depression by driving chronic inflammation in the skin and neuroinflammation in the central nervous system." (PMID 40141110, 2025). "Salivary interleukins, including IL-1β, IL-6, TNF-α, and IL-17, offer significant results as non-invasive biomarkers for early detection, severity assessment, and treatment monitoring of psoriasis, effectively reflecting systemic inflammation." (PMID 40731810, 2025). "The study aimed at analyzing the clinical profile of patients and non-specific inflammatory markers in terms of the response to the psoriasis treatment with IL-17, IL-23, IL-12/23, and TNF-α inhibitors." (PMID 41226807, 2025). "TNF-α is a central cytokine in the inflammatory cascade and has long beenimplicated in the pathogenesis of psoriasis." (PMID 41393395, 2025). "The rationale for investigating these biomarkers stems from studies demonstrating that serum levels of TNF-α, IL-17A, IL-17F, and IL-12/23 play a critical role in the development of psoriasis clinical manifestations and response to treatment." (PMID 40699767, 2025). "This upregulates the expression of inflammatory cytokines such as IL-1β and TNF-α, thereby promoting the development of psoriasis lesions." (PMID 41383588, 2025). "Ustekinumab appears to have one of the highest incidences of biologic-induced BP among psoriasis treatments, particularly in patients who previously failed anti-TNF-α therapy." (PMID 40422272, 2025). "Next, to better simulate the inflammatory cascade characteristic of psoriasis, we stimulated KCs with a combination of IL‐22, IL‐17A and TNF‐α, known to synergistically enhance the proinflammatory effects of IL‐22 in KCs." (PMID 40038877, 2025). "It was already reported that the levels of IFN-γ-secreting Th1 cells and IL-17/IL-22-secreting Th17 cells increase in patients who developed TNF-α-inhibitor-induced psoriasis." (PMID 40709177, 2025). "The in vitro models primarily involved HaCaT keratinocytes stimulated by psoriasis serum-derived exosomes, IL-17A, or TNF-α combined with IL-17A to mimic psoriatic conditions." (PMID 41007656, 2025). "- Psoriasis exhibits a clear Th17 dominance, with IL-17 and TNF-α synergizing to amplify keratinocyte hyperproliferation and antimicrobial peptide expression." (PMID 41479908, 2025). "In one series of psoriasis patients, those exposed to TNF inhibitors had a significantly higher likelihood of developing inflammatory myopathy than those never treated with biologics." (PMID 40861474, 2025). "Immunologically, psoriasis is driven by the activation of Th17 and Th1 cells, which secrete cytokines such as IL-17A, IL-22, and TNF-α." (PMID 40558675, 2025). "Our baseline characteristics reflect this, as the IL-17 inhibitor group had more patients with psoriasis than the TNF inhibitor group." (PMID 40615873, 2025). "KEGG pathway analysis further implicated the TNF and PPAR signalling pathways in psoriasis pathogenesis." (PMID 41224720, 2025). "COVID-19 infection leads to the excessive production of pro-inflammatory cytokines, including ILs and TNF-α, which are pivotal in the pathogenesis of psoriasis." (PMID 41011460, 2025). "The patient was initially considered for treatment with Otezla (Apremilast), an oral medication for psoriasis, which works by reducing the production of proinflammatory cytokines, including TNF-α." (PMID 40310305, 2025). "Inhibitors targeting TNF-α, IL-17, and IL-23 are widely used in clinical practice for the maintenance treatment of moderate-to-severe psoriasis." (PMID 41464777, 2025). "TNF-α is known to trigger inflammation and promote angiogenesis, both of which are key features of psoriasis pathology." (PMID 40507893, 2025).